MAP3K20 (mitogen-activated protein kinase kinase kinase 20)
Description:
Stress-activated component of a protein kinase signal transduction cascade that promotes programmed cell death in response to various stress, such as ribosomal stress, osmotic shock and ionizing radiation. Acts by catalyzing phosphorylation of MAP kinase kinases, leading to activation of the JNK (MAPK8/JNK1, MAPK9/JNK2 and/or MAPK10/JNK3) and MAP kinase p38 (MAPK11, MAPK12, MAPK13 and/or MAPK14) pathways. Activates JNK through phosphorylation of MAP2K4/MKK4 and MAP2K7/MKK7, and MAP kinase p38 gamma (MAPK12) via phosphorylation of MAP2K3/MKK3 and MAP2K6/MKK6. Involved in stress associated with adrenergic stimulation: contributes to cardiac decompensation during periods of acute cardiac stress. May be involved in regulation of S and G2 cell cycle checkpoint by mediating phosphorylation of CHEK2. [Isoform ZAKalpha]: Key component of the stress-activated protein kinase signaling cascade in response to ribotoxic stress or UV-B irradiation. Acts as the proximal sensor of ribosome collisions during the ribotoxic stress response (RSR): directly binds to the ribosome by inserting its flexible C-terminus into the ribosomal intersubunit space, thereby acting as a sentinel for colliding ribosomes. Upon ribosome collisions, activates either the stress-activated protein kinase signal transduction cascade or the integrated stress response (ISR), leading to programmed cell death or cell survival, respectively. Dangerous levels of ribosome collisions trigger the autophosphorylation and activation of MAP3K20, which dissociates from colliding ribosomes and phosphorylates MAP kinase kinases, leading to activation of the JNK and MAP kinase p38 pathways that promote programmed cell death. Less dangerous levels of ribosome collisions trigger the integrated stress response (ISR): MAP3K20 activates EIF2AK4/GCN2 independently of its protein-kinase activity, promoting EIF2AK4/GCN2-mediated phosphorylation of EIF2S1/eIF-2-alpha. Also part of the stress-activated protein kinase signaling cascade triggering the NLRP1 inflammasome in response to UV-B irradiation: ribosome collisions activate MAP3K20, which directly phosphorylates NLRP1, leading to activation of the NLRP1 inflammasome and subsequent pyroptosis. NLRP1 is also phosphorylated by MAP kinase p38 downstream of MAP3K20. Also acts as a histone kinase by phosphorylating histone H3 at 'Ser-28' (H3S28ph). [Isoform ZAKbeta]: Isoform that lacks the C-terminal region that mediates ribosome-binding: does not act as a sensor of ribosome collisions in response to ribotoxic stress. May act as an antagonist of isoform ZAKalpha: interacts with isoform ZAKalpha, leading to decrease the expression of isoform ZAKalpha.
Synonyms: MRK; MLK7; MLTK; ZAK; MLTKalpha; MLTKbeta; AZK; CNM6; MLT; SFMMP; mlklak; pk
Tractability: Small molecule: a structure with a bound ligand is known; a high-quality ligand is known; it belongs to a druggable protein family. PROTAC: it is named in the literature on targeted protein degradation; ubiquitination databases record sites on it; a small molecule that binds it is known.
Target class: TKL protein kinase group; Protein Kinase; Enzyme; TKL protein kinase MLK family; Kinase; TKL protein kinase MLK subfamily
Gene: Protein-coding gene on chromosome 2 (173,075,322 to 173,268,909, forward strand). Ensembl gene ENSG00000091436.
Subcellular location: Cytoplasm; Nucleus
Subcellular location (Human Protein Atlas): Cytosol
Gene Ontology:
Molecular function: ATP binding; JUN kinase kinase kinase activity; magnesium ion binding; MAP kinase kinase kinase activity; protein binding; protein kinase activator activity; protein serine kinase activity; protein serine/threonine kinase activity; ribosome binding; RNA binding; small ribosomal subunit rRNA binding; protein kinase activity
Biological process: cellular response to gamma radiation; cellular response to UV-B; DNA damage checkpoint signaling; embryonic digit morphogenesis; GCN2-mediated signaling; inflammatory response; JNK cascade; limb development; MAPK cascade; p38MAPK cascade; positive regulation of apoptotic process; positive regulation of mitotic DNA damage checkpoint; positive regulation of programmed cell death; protein autophosphorylation; protein phosphorylation; pyroptotic inflammatory response; stress-activated MAPK cascade; stress-activated protein kinase signaling cascade; cell death; cell differentiation; chromosome segregation; regulation of mitotic metaphase/anaphase transition; intracellular signal transduction
Cellular component: cytoplasm; cytosol; nucleus
Genetic constraint (gnomAD): Loss-of-function variants: 30 observed, 71.56 expected, observed/expected ratio (o/e) 0.42, 90% interval 0.31 to 0.57. The upper end of that interval is the gene's LOEUF score, 0.57, which puts it in group 2 of 6, group 1 being the genes least tolerant of losing a copy. Missense variants: 727 observed, 875.35 expected, observed/expected ratio (o/e) 0.83, 90% interval 0.78 to 0.88. Synonymous variants: 305 observed, 305.58 expected, observed/expected ratio (o/e) 1, 90% interval 0.91 to 1.1.
Gene-disease validity (ClinGen):
ClinGen rates the evidence that MAP3K20 causes each of these diseases.
myopathy, centronuclear, 6, with fiber-type disproportion (autosomal recessive): Strong.
Homologues: Orthologues: macaque MAP3K20 (99% identical), chimpanzee MAP3K20 (97% identical), pig MAP3K20 (93% identical), mouse Map3k20 (92% identical), dog MAP3K20 (92% identical), rat Map3k20 (92% identical), rabbit MAP3K20 (92% identical), guinea pig MAP3K20 (75% identical), zebrafish map3k20a (59% identical), Caenorhabditis elegans zak-1 (26% identical). Paralogues in human: MAP3K9 (19% identical), MAP3K10 (18% identical), MAP3K21 (18% identical), MAP3K11 (17% identical), MAP3K12 (16% identical), MAP3K13 (16% identical), RIPK3 (14% identical), TESK2 (14% identical), TESK1 (14% identical), LRRK2 (13% identical), RIPK1 (13% identical), TNNI3K (13% identical), and 11 more.
Diseases named in the same sentence as MAP3K20 in open-access papers:
MAP3K20 is named in the same sentence as 36 diseases in open-access papers, as found by Europe PMC text mining. Sharing a sentence is not in itself a finding about the gene and the disease. The quoted sentences say what the papers report.
colorectal cancer (2 papers, 2018 to 2021). A primary or metastatic malignant neoplasm that affects the colon or rectum. "PRPF6, a U5 snRNP, is another splicing factor frequently overexpressed in cancer cell lines, including colorectal carcinoma leading to the aberrant splicing of the oncogenic form of the mitogen-activated protein kinase 20 (MAP3K20)." (PMID 34888349, 2021).
diabetes (2 papers, 2025 to 2026). "These regions spanned genes (e.g., CCDC42, GYPE, MAP3K20, and OBI1) related to diseases (e.g., malaria infection and diabetes) with differing prevalence and incidence between populations." (PMID 41224710, 2025).
lung carcinoma (1 paper, 2023). "Radiation upregulated miR-155-5p in lung cancer cells, suggesting that miR-155-5p may improve radiosensitivity, and its radiation targets MAP3K20, GTF2H5, GATA3, and MDM2 were identified." (PMID 37569824, 2023). "Therefore, miR-92a-3p enhanced the radiosensitivity of lung cancer cells, and its radiation targets RNF4, MAP3K20, and NIPBL were identified." (PMID 37569824, 2023).
cancer (3 papers, 2018 to 2024). A tumor composed of atypical neoplastic, often pleomorphic cells that invade other tissues. "Finally, high MAP3K20 expression has been found to promote cancer progression in gastric, breast, bladder, and colorectal cancers." (PMID 38714855, 2024).
MAP3K20 also shares sentences with these, for which no sentence is quoted: tumor (5 papers); breast carcinoma (2); developmental delay (2); glioma (2); hepatocellular carcinoma (2); myopathies (2); scoliosis (2); bladder cancer (1); breast invasive carcinoma (1); cardiac diseases (1); cervical squamous cell carcinoma (1); chronic myeloid leukemia (1); colon cancer (1); colonic inflammation (1); congenital myopathy (1); dermatitis (1); ependymoma (1); glioblastoma (1); heart failure (1); lung adenocarcinoma (1); lupus (1); lymph node metastasis (1); medulloblastoma (1); melanoma (1); myofibrillar myopathy (1); neuroblastoma (1); neuromuscular genetic disease (1); Obesity (1); osteosarcoma (1); pancreatic cancer (1).
A further 2 diseases each share a sentence with MAP3K20 in 1 paper.